EGFR (epidermal growth factor receptor)
Diseases named in the same sentence as EGFR in open-access papers (continued):
Sharing a sentence is not in itself a finding about the gene and the disease.
lung cancer (continued). "Both temsirolimus and everolimus inhibited the phosphorylation of p70S6K and 4E-BP1, which are downstream targets of the mTOR pathway, and reduced the viability of EGFR mutant lung cancer cells, PC-9, and HCC827, even in the presence of HGF in vitro." (PMID 23690929, 2013). "We constructed Strep-HA-tagged versions of exon 19 deletion E746-A750 EGFR, which were then expressed in lung cancer cells using retroviruses." (PMID 24189400, 2013). "Recently, it was demonstrated that knockdown of Fas specifically enhanced cell death induced by the EGFR tyrosine kinase inhibitor in EGFR-mutant lung cancer cells and Fas signaling promotes tumor growth through the JNK and Jun pathway." (PMID 23232551, 2013). "We performed a comprehensive analysis of EGFR/KRAS mutation and ALK rearrangement in a total of 360 surgically resected lung cancers." (PMID 23936355, 2013). "Our data provide evidence that induction of the EMT contributes to the acquired resistance to EGFR-TKIs in lung cancer." (PMID 23520479, 2013). "The growth of tongue cancer HSC-3 and lung cancer A549 cell lines treated with EGFR-TKI was assessed by MTT assay." (PMID 23592411, 2013). "We showed here that EGFR expression and activation were elevated in lung cancer cells that survived IR, and this elevation was required for their increased invasiveness." (PMID 23951036, 2013). "Studies focusing on EGFR and ErbB1 in lung cancer cells are required for a better understanding of the functions of EGFR in tumor biology and for the development of new drugs and new treatment guidelines." (PMID 23631593, 2013). "Our results also suggest that mTOR inhibitors have advantage of several mechanisms to suppress the growth of EGFR-TKI resistance triggered by HGF in EGFR mutant lung cancer cells." (PMID 23690929, 2013). "The resulting mutant EGFR interactome reference map was used to functionally interrogate targets in EGFR-mutant lung cancer cell lines, leading to identification of new targets important for EGFR-driven survival." (PMID 24189400, 2013). "To increase confidence in identified functional proteins and to minimize off-target effects, we interrogated three EGFR-addicted lung cancer cell lines (PC9, HCC827, and HCC4006)." (PMID 24189400, 2013). "Our results identified a core network consisting of 14 proteins required for the survival of multiple EGFR-addicted lung cancer cell lines." (PMID 24189400, 2013). "In another example, gefitinib and erlotinib are often used to target epidermal growth factor receptor for the treatment of non–small-cell lung cancer." (PMID 23437217, 2013). "Exon 19 deletion E746-A750 mutant forms of EGFR were used as a bait for TAP-MS experiments in lung cancer cells harboring mutant EGFR proteins and highly sensitive to EGFR TKI." (PMID 24189400, 2013). "AXL was thought to play a key role in the acquisition of the resistance to EGFR inhibitor in lung cancer." (PMID 24344100, 2013). "Another association with the EMT has been found in epidermal growth factor receptor (EGFR)-targeting drugs for the treatment of lung cancer." (PMID 23634282, 2013). "Restoration of Akt activation eventually reduces sensitivity of the lung cancer cells to EGFR interruption." (PMID 24280348, 2013). "Since Lyn was highly expressed in the Calu3 lung cancer cell line, a role for Lyn in EGFR constitutive phosphorylation was investigated." (PMID 23866081, 2013). "In an initial attempt to validate our mathematical model, we treated an EGFR mutant lung cancer cell line with several concentration of the clinically used EGFR inhibitor Gefitinib." (PMID 23365639, 2013). "Treatment with epidermal growth factor receptor tyrosine kinase inhibitors (EGFR-TKIs), such as gefitinib and erlotinib, has achieved high clinical response rates in patients with non–small cell lung cancers (NSCLCs)." (PMID 24223798, 2013).
lung cancer (continued). "It has been recently reported that inhibition of EGFR by erlotinib activates the STAT3/Bcl2/Bcl-XL survival signaling pathway in human lung cancer." (PMID 24019973, 2013). "We have shown here for the first time that bufalin restored EGFR-TKIs sensitivity in resistant lung cancer cells via inhibition of Met/PI3K/Akt and activation of death signaling." (PMID 23533466, 2013). "In the current study, we explored therapeutic effects of EGFR tyrosine kinase inhibition, using two EGFR-TKIs and an αEGFR antibody, in human tongue and lung cancer cell lines." (PMID 23592411, 2013). "For example, detecting the T790M mutation in blood samples would be useful for patient selection for treatment with new EGFR-TKIs for lung cancers that are resistant to gefitinib and erlotinib." (PMID 24278442, 2013). "PC-9 and HCC827, the EGFR mutant human lung cancer cell lines with EGFR exon 19 deletion, were highly sensitive to gefitinib." (PMID 23533466, 2013). "Downregulation using siRNA and/or inhibition of EPS8 by mithramycin resulted in decreased greater cell growth inhibition in non-EGFR mutant lung cancer cells and a bladder cell line following cisplatin treatment." (PMID 24367505, 2013). "It has been reported that Bim was critical for erlotinib-induced apoptosis in EGFR mutant lung cancer cells and imatinib-induced apoptosis in KIT dependent GIST cells." (PMID 24009732, 2013). "Mutations in the kinase domain of epidermal growth factor receptor (EGFR) have high levels of basal receptor phosphorylation and are associated with clinical responsiveness to Iressa in patients with nonsmall cell lung cancer (NSCLC)." (PMID 23956990, 2013). "The PIK3CA pathway consist of the KRAS and EGFR genes which are important targets for many cancers, mutations of PIK3CA have been also identified in lung cancer." (PMID 24369052, 2013). "Recently, targeted anticancer drugs, including EGFR-TKIs, have been approved for the treatment of lung cancer." (PMID 23420122, 2013). "Inhibition of uncontrolled EGFR expression improved treatment of malignant diseases, such as breast and lung cancers." (PMID 23449029, 2013). "We previously reported that HGF induces EGFR-TKI-resistance in EGFR mutant lung cancer cells by restoring MET/PI3K/AKT pathway signaling." (PMID 23690929, 2013). "We previously reported that HGF activates the MET/GAB1 pathway and increases VEGF production by EGFR mutant lung cancer cells." (PMID 23690929, 2013). "We investigated the correlation between plasma pro-inflammatory cytokines (including plasma RANTES, IL-10, and IL-8) levels and clinical outcomes following EGFR-TKI treatment in lung cancer patients." (PMID 23566546, 2013). "Targeting oncogenic pathways has led to recent exciting advances in multiple cancers, including vemurafenib in BRAF mutant melanoma, erlotinib in EGFR mutant non-small cell lung cancer, and crizotinib in lung cancer with the EMLA4-ALK translocation." (PMID 23593290, 2013). "The Departments of Biochemistry and Pathology are labelled and funded by the French National Cancer Institute (INCa) to perform EGFR testing of lung cancer patients." (PMID 23934203, 2013). "In the present study, we demonstrated that mTOR inhibitors suppressed the growth of EGFR mutant lung cancer cells, even in the presence of HGF, in vitro and in vivo." (PMID 23690929, 2013). "Preclinical activity for afatinib (BIBW2992), a second irreversible inhibitor of EGFR and ERBB2, was demonstrated in Ba/F3 cells expressing an ERBB2-mutant with an insertional mutation at codon 776 and in transgenic lung cancer models." (PMID 23630663, 2013). "Although EGF receptor tyrosine kinase inhibitors (EGFR-TKI) have shown dramatic effects against EGFR mutant lung cancer, patients ultimately develop resistance by multiple mechanisms." (PMID 24386407, 2013).
lung cancer (continued). "Although irreversible EGFR-TKIs such as afatinib have been tested in clinical trials for EGFR-TKI-refractory lung cancer, monotherapy with agents of this class has shown minimum benefits with severe adverse effects." (PMID 24386407, 2013). "Here, we present evidence showing that acquired resistance to, EGFR-tyrosine kinase inhibitor, erlotinib in lung cancer is mediated by the epithelial–mesenchymal transition (EMT)." (PMID 23520479, 2013). "Considering these factors, the development of drugs that target this protein, i.e., EGFR inhibitors, for use in the treatment of lung cancer is gaining importance." (PMID 23631593, 2013). "The increased response rate and progression free survival observed here in patients with lung cancer whose tumors demonstrated a low Mig6/EGFR ratio are dramatic." (PMID 23935914, 2013). "Lung cancer cells were treated with the single EGFR TKIs gefitinib, erlotinib, or afatinib, and in combination with c-MET inhibitor su11274." (PMID 23527257, 2013). "Notch3 affects apoptosis and tumor growth in lung cancer by co-operating with the EGFR-MAPK pathway." (PMID 23426998, 2013). "Because the EGFR interactome is highly dependent on cell context, this approach offers the best chance of recovering pertinent proteins and mechanisms, a potential flaw in using cells other than lung cancer cells driven by mutant EGFR." (PMID 24189400, 2013). "GRB2, SHC1, ERRFI, and UBS3B were found both in EGFR-mutant lung cancer cell lines and in AALE cells with mutant EGFR as a bait and thus represented logical choices to further examine as secondary baits." (PMID 24189400, 2013). "We previously reported that this pathway is also crucial for acquiring HGF-triggered resistance to EGFR-TKIs in EGFR mutant lung cancer cells." (PMID 23690929, 2013). "For example, a significant number of EGFR wild-type tested lung cancer patients respond to EGFR-TKIs." (PMID 27605195, 2013). "The signaling pathways triggered by EGFR are critical to lung cancer as blocking with specific inhibitors results in cell death." (PMID 23866081, 2013). "One frequent characteristic of lung cancer is an aberration in which one or more receptor tyrosine kinases (RTKs), such as MET, EGFR, and ALK, are commonly overexpressed, amplified, or mutated." (PMID 23844053, 2013). "Lung cancer cells frequently manifest alterations in their molecular genetics, including changes in epidermal growth factor receptor (EGFR) expression." (PMID 23631593, 2013). "The success of small molecules specifically inhibiting EGFR function in mutant EGFR-driven lung adenocarcinoma has promoted molecular targeted therapy for lung cancer." (PMID 23976985, 2013). "These techniques were also used for the prediction of specific miRNAs targeting the epidermal growth factor receptor (EGFR) in lung cancer." (PMID 23016851, 2013). "For a subset of lung cancers with acquired resistance to epidermal growth factor receptor-targeting therapy, MET amplification is one of the most frequently involved mechanisms." (PMID 23379953, 2013). "Research data showed that over 50%–70% of lung cancer, colon cancer and breast cancer have high expression of EGFR." (PMID 23613900, 2013). "It was recently reported that miR-145 inhibits expression of EGFR and reduces cell growth of lung cancer cells." (PMID 23076445, 2013). "Adequate methods to identify which lung cancer patients are most likely to benefit from the targeted drugs against both epidermal growth factor receptor/epidermal growth factor (EGFR/EGF) are needed." (PMID 26317020, 2013). "Numerous mutations and variants in the epidermal growth factor receptor (EGFR) gene have been demonstrated to be associated with the occurrence, metastasis and prognosis of various types of tumors, including lung cancer." (PMID 24137392, 2013). "The progression-free survival of EGFR mutant lung cancer patients was also much longer than that of unselected NSCLC patients." (PMID 23690929, 2013).
lung cancer (continued). "A clinical trial has revealed that lung cancer cells with strong E-cadherin expression exhibit a significantly longer time to progression after EGFR-tyrosine kinase inhibitor (EGFR-TKI) treatment." (PMID 23634282, 2013). "Targeting EGFR in lung cancer is particularly successful in patients with activation mutations in ErbB1, while other NSCLC patients either are partially responsive, have disease stabilization, or do not respond at all." (PMID 23866081, 2013). "Our current study is preclinical, and we demonstrated that mTOR inhibitors showed considerable efficacy in lung cancer cells with HGF-mediated resistance to EGFR-TKI resistance both in vitro and in vivo." (PMID 23690929, 2013). "MET amplification is rare in lung cancer but is seen in up to 20% of tumors treated with EGFR TKIs and contributes to EGFR-TKI resistance." (PMID 23936763, 2013). "Using an EGFR mutant lung cancer cell line, we showed that inhibition of EGFR leads to a reduction in miR-9 as well as c-MYC expression." (PMID 23365639, 2013). "In our case, the tumor is characterized by the typical molecular profile of lung carcinomas arising in smokers, with EGFR and ALK wild type phenotype." (PMID 23844609, 2013). "The ability of ior egf/r3 Mab to recognize human EGFR in frozen lung carcinoma tissues by immunohistochemistry was previously reported." (PMID 26317020, 2013). "EGFR, KRAS, and BRAF mutations and EGFR antibody treatment (colorectal carcinoma) and EGFR inhibitor treatment (lung carcinoma) serve as good examples." (PMID 24764475, 2013). "Two different human lung cancer cell lines were used in the lower transwell chambers: A549, a lung carcinoma cell line harboring a K-Ras mutation and HCC827, a lung adenocarcinoma cell line with an EGFR mutation (E746-A750 del)." (PMID 23762239, 2013). "To identify the potential mechanisms of resistance, we established cell lines resistant to EGFR-TKIs from the human lung cancer cell lines PC9 and11–18, which harbored activating EGFR mutations." (PMID 22815900, 2012). "Currently, there are only a few reports on the biological effects of EGFR siRNAs on lung cancer cells." (PMID 22436374, 2012). "In conclusion, our study has provided evidence that miR-23a regulated TGF-β-induced EMT by suppression of E-cadherin and contributed to EGFR-TKI resistance in lung cancer cells." (PMID 22752005, 2012). "Based on recent data and understanding of the genetic basis of lung cancer, EGFR, K-ras, ALK, MET, CBL, and COX2 are being used as therapeutic targets." (PMID 25562699, 2012). "The aim of the present study is to investigate the influence of I3C on radiosensitivity in epidermal growth factor receptor (EGFR)-positive and EGFR-negative lung cancer cell lines." (PMID 22814257, 2012). "The present review predominantly discusses significance of EGFR, miRNA, autophagy and cancer stem cell in lung cancer therapy." (PMID 22489192, 2012). "EGFR-independent upregulation of pAKT by hypoxia has also been observed in lung cancer cells, whereby activation of AKT was induced via the IGF1R/PI3K/AKT pathway." (PMID 23046567, 2012). "In lung cancer, molecular analysis of the epidermal growth factor receptor gene in CTC provides important information regarding therapeutic response and prognosis." (PMID 22281663, 2012). "A recent report demonstrated that knockdown of several components of the NF-kB pathway specifically enhanced cell death induced by the EGFR TKI erlotinib in EGFR-mutant lung cancer cells." (PMID 22615840, 2012). "Second, because only a relatively small number of patients received EGFR mutation analysis, the results of EGFR mutation and EGFR-TKI treatment in the young lung cancer patients should be interpreted carefully." (PMID 22695392, 2012). "In one study, an EGFR mutant lung cancer cell line (HCC827) was rendered resistant to gefitinib by exogenous heregulin." (PMID 23691449, 2012).
lung cancer (continued). "The vascular endothelial growth factor (VEGF) and epidermal growth factor receptor (EGFR) are of two molecules extensively studied for developing novel agents in the targeted therapy of lung cancer." (PMID 23443092, 2012). "This is supported by the findings that EGFR promoter hypermethylation occurs in solid tumour cell lines, e.g. breast, colon and lung cancers." (PMID 22264301, 2012). "EGFR upregulation appeared to be selectively expressed in a number of tumors as glioblastomas and lung cancer." (PMID 22300665, 2012). "There is a large body of accumulated evidence that the epidermal growth factor receptor (EGFR) and its family members are heavily involved in the development and progression of numerous human tumors, including lung cancer." (PMID 23226726, 2012). "Additional functional analyses of this SNP are needed to better understand the mechanism by which the 8227G/A SNP of EGFR affects lung cancer." (PMID 23226726, 2012). "There are already several examples of such personalized treatments including the drug Gleevec that targets the BCR-ABL fusion gene in chronic myelogenous leukemia (CML) and Iressa that targets the EGFR gene in lung cancer." (PMID 23300412, 2012). "The understanding of EGFR status in lung cancer and the development of gefitinib is a milestone in personalized therapy in lung cancer." (PMID 26316937, 2012). "This is the first evidence that EGFR is involved in the regulation of FASN expression in a lung cancer model with EGFR-overexpression." (PMID 22769244, 2012). "Similar to the lung cancer models, sensitivity to EGFR TKIs was increased by co-treating these cells with Met TKIs." (PMID 22788954, 2012). "Gefitinib's anti-lung cancer effects attribute to its binding to the adenosine triphosphate binding site in the tyrosine kinase domain of EGFR, thereby inhibiting EGFR kinase activity." (PMID 23185274, 2012). "Epidermal growth factor receptor (EGFR) - tyrosine kinase inhibitor (TKI) is used for the patients with EGFR-mutant lung cancer." (PMID 23181703, 2012). "He discovered that miR-145 plays an important role in inhibiting lung cancer proliferation by targeting EGFR and NUDT1." (PMID 23369397, 2012). "Our results showed that the patients with the 8227GA or AA type in intron 1 had a significantly better prognosis with the anti-EGFR therapy than the patients with the GG type (p=0.0448) in terms of recurrence of lung cancer." (PMID 23226726, 2012). "Further investigation is necessary to clarify the role and genesis of these histological transformations in EGFR inhibitor resistance in lung cancer patients." (PMID 22970367, 2012). "In lung cancer, the well-developed epidermal growth factor receptor (EGFR) and the newly emerging EML4-anaplastic lymphoma kinase (ALK) are important therapeutic targets." (PMID 23109866, 2012). "Recently, three groups independently discovered that activation of the AXL receptor tyrosine kinase confers acquired resistance to erlotinib in both cell culture and tumor xenograft models of EGFR mutant lung cancer." (PMID 22970367, 2012). "In contrast to the radioresistance conferred by EGFR overexpression, the radiosensitivity of lung cancer cells with mutant EGFR has been demonstrated in vitro." (PMID 23110940, 2012). "In lung cancer, resistance to EGFR TKIs correlates with amplification of the hepatocyte growth factor (HGF) receptor tyrosine kinase Met." (PMID 22788954, 2012). "Lung cancer cells acquire dependence on EGFR activity for survival, substantiating the use of EGFR inhibitors for lung cancer therapy." (PMID 22457794, 2012). "Another study on lung cancer found miR-7 to be an oncogenic miRNA, as EGFR was found to induce miR-7 expression through a Ras/ERK/Myc pathway, which promoted cell growth and tumor formation, indicating an indirect feedback loop." (PMID 22623953, 2012).